IL6 (interleukin 6)
Diseases named in the same sentence as IL6 in open-access papers (continued):
Sharing a sentence is not in itself a finding about the gene and the disease.
COVID-19 (continued). "Recently, Shi and others (2020b) found higher serum concentrations of MMP-3 in COVID-19 patients than in healthy individuals, and their levels correlated with inflammatory markers such as IL-6 and IL-1β." (PMID 35647937, 2022). "Three studies demonstrated a high proportion of CD14+ and CD16+ cells in patients with severe COVID-19, with inflammatory factors including GM-CSF and IL-6, IL-10 and TNF-α." (PMID 35843719, 2022). "Among these, we observed a significant decrease in the three best documented general pro-inflammatory markers in COVID-19: IL-6, IL-1β and TNF-α." (PMID 36466830, 2022). "The integrated areas of the regions related to IFN-γ, TNF-α, IL-1 β, IL-6, and IL-10 were obtained to elucidate the quantity of those cytokines in the V-COVID-19 and V-Healthy groups." (PMID 36497139, 2022). "In the COVID-19 context, one of the first targets was IL-6 because reports showed that high serum levels of this cytokine correlated with severity." (PMID 35631442, 2022). "The major immune signals that are impaired in COVID-19 at the transcriptional and translational levels are pro-inflammatory IL-6 signaling and the type-1 interferon system." (PMID 35957811, 2022). "Nevertheless, in the present study, IFN-γ, IL-4, IL-5, IL-6, and IL-10 were the only cytokines elevated in patients with COVID-19." (PMID 34987205, 2022). "We also present evidence for incomplete IL-6 inhibition in patients with severe COVID-19 treated with tocilizumab." (PMID 35928820, 2022). "IL-6 has been frequently measured in COVID-19 patients, but elevated levels of IL-6 were less frequent, as compared to other parameters." (PMID 35327468, 2022). "Interleukin 6 (IL-6) is thought to be the key point of endotheliopathy and coagulopathy, and some researchers have studied its influence in the development of COVID-19-related liver damage [19▪▪]." (PMID 35098930, 2022). "Another similar research found that the level of IL-6 was noticeably higher in 86.8% of hospitalized COVID-19 individuals with severe complications and 22.9% had more than a tenfold increment in IL-6 levels." (PMID 35619180, 2022). "They advanced that estimation of interleukin-6 would aid the clinician in prognosticating COVID-19 as it is significantly higher in severe cases than controls." (PMID 35261542, 2022). "Our data supports that the uptake of cell corpses infected with SARS-CoV-2 exacerbates the secretion of inflammatory IL-6 and IL-1β, suggesting a mechanism for the robust secretion of cytokines related to COVID-19 cytokine storm." (PMID 35666101, 2022). "When stimulated in vitro, the monocytes from COVID-19 patients synthesized significantly lower levels of pro-inflammatory cytokines IL-1β, TNFα, IL-6, and MCP-1, compared to the cells obtained from apparently healthy donors." (PMID 35632823, 2022). "Patients with COVID-19 had significantly higher CSF concentrations of neopterin, β2M, interleukin (IL) 2, IL-6, IL-10, and tumor necrosis factor α (TNF-α) compared with controls." (PMID 35604688, 2022). "Elevated IL-6 levels and hyperferritinemia are considered indicators of systemic inflammation and poor prognosis in COVID-19." (PMID 36012968, 2022). "It has been reported that IL-8 and IL-6 are closely correlated with COVID-19 severity (moderate to end-organ damage)." (PMID 35782361, 2022). "The authors noted that 80% of COVID-19 studies report mean IL-6 concentrations lower than 100 pg/mL." (PMID 36289881, 2022). "Our aim was to evaluate the relationship between SARS-CoV-2 viremia and time evolution of IL6 levels in a COVID-19 prospective cohort." (PMID 35783606, 2022). "The average IL-6 concentration was higher in patients with COVID-19 than in normal controls, whereas IL-3 showed the opposite behavior." (PMID 36129990, 2022). "The elevation of NP levels was supposed to be distinct from those of CRP and IL-6 in relatively early and mild COVID-19 patients." (PMID 35529699, 2022).
COVID-19 (continued). "This framework releases large amounts of pro-inflammatory cytokines, as in COVID-19, including IL-6, TNF, IL-1β, IL-12, IL-17, IL-18, IP-10, IFN-γ, CCL2 and CCL5." (PMID 35843719, 2022). "For instance, the IL-6 was the most specific predictor (specificity 95.3%) with a high sensitivity (97.0 %) for COVID-19 severity, based on a cut-off of 84.1 pg/mL and an area under the curve (AUC) of 0.675 (95% CI: 0.588-0.761)." (PMID 35464048, 2022). "MiR-451a, mostly expressed in blood cells and released in extracellular vesicles, attenuates type I IFN and IL-6 responses and was reported to progressively decrease with COVID-19 severity." (PMID 36032130, 2022). "CRS mediated by IL-6 is prevalent among COVID-19 patients and is accountable for their severe acute respiratory distress." (PMID 35992697, 2022). "We found that while many cytokines, including IL-6, showed an impact on the prognosis of COVID-19 patients, only two of them, IL-1RA and IL-10, were of clinical significance in the subgroup of patients receiving tocilizumab therapy." (PMID 35887283, 2022). "This correlation presented the rationale for using IL-6-blockade therapy to improve survival for COVID-19 patients in the intensive care unit (ICU)." (PMID 35626318, 2022). "With no adverse effects, CP treatment can reduce mortality and improve breath and inflammatory cytokines IL-6 and Ferritin in COVID-19." (PMID 36248407, 2022). "Ferritin (macrophage activation indicator) and IL-6 (T lymphocyte activation) are known to suspect cytokine storm syndrome in severe COVID-19 exacerbation." (PMID 36518574, 2022). "In fact, by shifting RAAS toward ANGII/AT1R, the level of inflammatory cytokines such as IL4, IL10 and IL6 are increased, which in turn activates T-cells in peripheral blood of COVID-19 patients." (PMID 36128671, 2022). "Significant effort has been made to prove the potential role of IL-6 as a prognostic marker of mortality in patients with COVID-19 and their need for mechanical ventilation." (PMID 35464749, 2022). "Early responses of elevated cytokines such as IL-6 reflect the active immune responses, leading to high titers of IgG antibodies against COVID-19." (PMID 35248063, 2022). "Increased IL-6 and granzyme B were found to predict liver injury in COVID-19 patients, whereas interferon-gamma (IFN-γ), IL-1 receptor-a (IL-1Ra) and PD-L1 were predictors of remarkable radiological findings." (PMID 35529862, 2022). "Earlier studies had indicated that severely/critically ill COVID-19 cases had elevated serum levels of interleukins (IL-1β, IL-2, IL-4, IL-6, IL-10)." (PMID 36415655, 2022). "IL-6 and CRP showed good discrimination in COVID-19, with an AUC of 0.794 (95%CI, 0.694–0.894) for IL-6 and 0.807 (95%CI, 0.721–0.893) for CRP." (PMID 35622838, 2022). "Studies show that COVID-19 patients have increased levels of numerous inflammatory cytokines, like IL-1 beta, IL-2, IL-6, TNF-alpha, etc. and these cytokines correlate with disease severity." (PMID 35629072, 2022). "In contrast to other biomarkers, such as IL-6, CRP, D-dimers, and ferritin, suPAR increases earlier in COVID-19 patients, reflecting a higher risk of disease progression to respiratory failure and respiratory failure mortality." (PMID 36038915, 2022). "Serum IP-10, MCP-1, CRP, IFNγ, IL-10, IL-13, IL-17α, IL-23, and IL-6 were significantly higher in COVID-19 patients compared to controls." (PMID 36554094, 2022). "The inflammatory markers fibrinogen (OR = 1.89; CI = 1.16–3.07), procalcitonin (OR = 2.32; CI = 1.29–3.88), D-dimers (OR = 3.14; CI = 2.06–4.38), and IL-6 (OR = 3.49; CI = 2.28–4.70) also showed a higher likelihood of developing psychoticism during COVID-19." (PMID 35682084, 2022). "In particular, COVID-19 patients show elevated IL-6 in their serum, even prompting the consideration of anti-IL-6 antibodies as a treatment." (PMID 35464419, 2022).
COVID-19 (continued). "In most studies, compared with healthy controls, COVID-19 patients had significantly higher levels of interleukin (IL)-2, IL-4, IL-6, IL-10, tumor necrosis factor (TNF)-α, and C-reactive protein (CRP) and lower lymphocyte counts." (PMID 35310853, 2022). "Accordingly, in our COVID-19 cohort, miR-21-5p levels showed positive correlations with serum IL-6 and CPK, which are biomarkers of inflammation and myocardial damage, respectively." (PMID 36032130, 2022). "The levels of TNFa, IL-6, IL-1b, IFNg, IL-2, and IL-10 have been reported as inflammatory cytokines in COVID-19." (PMID 35669157, 2022). "In this study of 90 ICU COVID-19 patients, we evaluated serum levels of four cytokines (IL-1β, IL-6, IL-10 and TNFα) as well as standard clinical and laboratory measurements." (PMID 36451808, 2022). "The major cytokines in COVID-19 pathophysiology, including IL-6, IL-8, and TNF-α, responded positively to PBM therapy and opened a new window for inhibiting and managing a cytokine storm within only 3-10 days." (PMID 35874678, 2022). "Self-reported persistent neurological problems during COVID-19 recovery were correlated with advanced age, comorbidities, and increased levels of IL6." (PMID 35625737, 2022). "Increased cytokine production, especially IL-1β, IL-6, and IL-10, is another critical characteristic of severe COVID-19." (PMID 36226148, 2022). "The literature suggests that IL-6 and IL-1β play a prominent role in the pathogenesis and severity of COVID-19, and that is why the IL-6 and IL1β antagonists are in a clinical trial." (PMID 36298704, 2022). "The same authors found CSF immunoreactivity from two females with MRI suggestive of encephalitis after COVID-19 onset, increased CSF IL-6 and good response to immunotherapy." (PMID 35353232, 2022). "Another research results showing that, patients with COVID-19 were also proved to have a high-level of interleukin 6 (IL-6)." (PMID 36172345, 2022). "IL-6, CRP, and IL-10 and have also been associated with disease severity amongst COVID-19 patients, correlating with severe clinical outcomes and fatality." (PMID 36268187, 2022). "Due to lack of studies showing integration of all the major roles of IL-6 in COVID-19 illness, here, we performed a longitudinal study showing the role of IL-6 in diagnosis, treatment, and prognosis of COVID-19-related disease." (PMID 36366295, 2022). "The IL-6 levels were elevated nearly threefold in complicated COVID-19 cases, and there were several systemic and extrapulmonary disorders not found in patients with uncomplicated disease." (PMID 35464491, 2022). "Our data suggest that NP synthesis is upregulated at the early phase of infection by a distinct pathway and/or cells from those of CRP and IL-6 in patients with COVID-19." (PMID 35529699, 2022). "Our results evidence that patients with COVID-19 residing in high-altitude tend to have higher levels of inflammatory cytokines, particularly IL-6, IL-10 and TNF-α." (PMID 35090394, 2022). "This article will address the current understanding of cytokines-induced alterations in COVID-19, focusing on interleukin (IL)-6, IL-1, IL-17, and tumor necrosis factor (TNF)." (PMID 35619180, 2022). "The importance of IL-6 and IL-10 as major pro- and antiinflammatory cytokines was shown in many trials on COVID-19 with meta-analyses showing the prevalent role of these two cytokines in disease severity and prognosis." (PMID 35887283, 2022). "Elevated levels of IL-6 have been reported as a biomarker for COVID-19-induced CRS, chimeric antigen receptor (CAR)-T therapy-induced CRS, and sepsis patients with worsening disease status." (PMID 36140141, 2022). "In patients with COVID-19, higher serum C-reactive protein, interleukin-6, and LDH levels, which correlated with disease severity, were observed in the diabetic group with hyperglycemia than in the non-diabetic group." (PMID 35836103, 2022). "This is potentially significant because IL-6, especially, is a major target for therapy in COVID-19." (PMID 36296272, 2022).
COVID-19 (continued). "Pharmacological treatment for COVID-19 included antivirals (45.6%), azithromycin (40.5%), hydroxychloroquine or similar drugs (37.9%), anti-IL6 or anti-IL6R monoclonal antibodies (19.1%), and convalescent hyperimmune plasma (10.1%)." (PMID 36028857, 2022). "This agent also reduces serum and lung IL-6 concentrations making it a good candidate for COVID-19 treatment (Lancaster and others 2017; Crisan-Dabija and others 2020)." (PMID 35647937, 2022). "The identification of which COVID-19 patients are suitable for treatment with IL-6 antagonists and TNF-α inhibitor are meaningful in the clinic." (PMID 35237162, 2022). "We believe the large number of purUUpurU in SARS-CoV-2 contributes to the markedly elevated levels of proinflammatory cytokines including IL-1, TNF, and interleukin 6 (IL-6) in severe COVID-19." (PMID 36420234, 2022). "IL-6 is often elevated in patients with COVID-19, and its level is positively correlated with COVID-19 mortality." (PMID 35276917, 2022). "First, due to the limitations of early disease identification and the urgency of controlling COVID-19, patients who were admitted early often lack laboratory data, such as IL-6, IL-10, IFN-γ and viral load." (PMID 35572983, 2022). "A previous study reported IL-6, IP-10 and IL-10 of first blood draw as predictors of COVID-19 clinical deterioration while antibody responses negatively correlated with deterioration." (PMID 35177626, 2022). "Among these, IL-6 was suggested as the key player in the cytokine storm observed during COVID-19 pathogenesis." (PMID 35645219, 2022). "In fact, IL-6 serum levels in patients affected by severe COVID-19 are about three times higher with respect to IL-6 levels of patients with mild disease presentation." (PMID 36289890, 2022). "IL-6 had the highest accuracy in distinguishing COVID-19 patients (AUC=1, P<0.001 at a cutoff of 0.359), followed by TUG1 (AUC=0.999, P<0.001 at a cutoff of 2.28)." (PMID 35982898, 2022). "For example, the mRNA expression of IL-6, which contributes to excessive inflammation in COVID-19, was decreased in lower lung lobes." (PMID 35252273, 2022). "The biological indicators used to assess responsiveness to infection in these COVID-19 patients were IgG and IL-6." (PMID 36355881, 2022). "Among hospitalized COVID-19 patients, the increase in AngII level is accompanied by an increased level of IL-6, with the highest mortality rate." (PMID 35265087, 2022). "In line with past studies, IL-6 levels were significantly higher in our sepsis cohort compared to COVID-19." (PMID 35723762, 2022). "Data analysis demonstrated that COVID-19 patients presented a clear pro-inflammatory storm, mediated by IL-6 and CXCL10 with the highest magnitude order (≥19x; ≥10x, respectively)." (PMID 36451835, 2022). "First, we identified a genome-wide significant difference of IL-6 rs2069837 (p = 9.73 × 10−15, OR = 0.41) between 437 critical patients with COVID-19 and 2551 normal controls in the discovery cohort." (PMID 35368020, 2022). "Despite certain medical societies’ recommendations against starting or continuing bDMARDs (including anti-TNF medications) in areas where COVID-19 has been circulating in the population, anti-IL-6 medications have been deemed to be safer." (PMID 35054471, 2022). "Several groups reported that severe COVID-19 is characterized by high levels of pro-inflammatory cytokines IL-6 and IL-1β7,19,31–34, while IFN responses are blunted, as shown by whole blood transcriptomics and plasma profiling." (PMID 35508575, 2022). "A study of a longitudinal serum cytokine analysis of 207 COVID-19 patients showed that in very early inflammatory responses, IL-6, TNF-a, IL-10, and IL-1b rose in those with more severe disease." (PMID 35223745, 2022). "DCs are key immune cells involved in severe COVID-19-induced lung damage mediated by aldosterone, which can stimulate DCs to produce IL-6 and transforming growth factor-β1 via the mineralocorticoid receptor." (PMID 35265087, 2022).
COVID-19 (continued). "Considering the pivotal role of IL-6 in COVID-19 pathogenesis and CRS condition, reducing the level of IL-6 can improve the clinical outcome in patients with COVID-19." (PMID 35619180, 2022). "Patients underwent psychophysical olfactory assessment with Connecticut Chemosensory Clinical Research Center test and IL-6 plasma level determination within 10 days of the clinical onset of COVID-19." (PMID 33983525, 2022). "Plasma proinflammatory cytokines, including IL-6 and tumor necrosis factor (TNF), and several chemokines, have been detected at elevated concentration in patients with COVID-19 and were associated with disease severity." (PMID 36439166, 2022). "A number of studies have shown that IL-6 is a new target for the treatment of COVID-19, and IL-6 inhibitors have the potential to treat COVID-19." (PMID 36204652, 2022). "In critically ill COVID-19 patients, seven of 10 patients had stable or decreased plasma IL-6 levels after steroid administration." (PMID 35228930, 2022). "The most common COVID-19-related renal complications are including acute tubular injury, collapsing glomerulopathy, thrombotic microangiopathy, complement activation and IL-6-induced renal vascular permeability." (PMID 36128671, 2022). "In conclusion, complete IL-6 antagonism is crucial to controlling disease activity in immune-dysregulated diseases such as COVID-19 and iMCD." (PMID 35928820, 2022). "Patients with severe COVID-19 exhibited elevated levels of interleukin-6 (IL-6), a VEGF synthesis inducer." (PMID 36140343, 2022). "Activated monocytes and monocyte-derived macrophages are considered a major source of IL-6, and high numbers of these cells are found in the lungs of patients with severe COVID-19." (PMID 35744777, 2022). "As observed in this study and others, IL-6, IL-8 and IL-10 have systematically been reported as increased in COVID-19, particularly in the acute phase of the disease." (PMID 36077133, 2022). "In fact, in our cohort with high IL-6 levels (and substantially free from repurposed drugs), QTc duration and QTc prolongation prevalence in patients with COVID-19 were significantly increased when compared to controls." (PMID 35665254, 2022). "Previous studies indicated that SARS-CoV-2 infection contributes to the increased serum levels of IL-6 in patients with severe COVID-19." (PMID 36363785, 2022). "In COVID-19, the timing of any anti-inflammatory intervention, such as with corticosteroids or IL-1/IL-6 inhibitors is critical." (PMID 36268783, 2022). "Among various immunosuppressive therapies that have been tried for cytokine storm, tocilizumab is an anti-interleukin-6 inhibitor that has been introduced as a novel treatment for severe COVID-19." (PMID 35101103, 2022). "The literature identifies TNF-α and IL-6 receptor inhibitors to be effective in treating COVID-19 among patients with rheumatic diseases as during recovery of COVID-19, decreased levels of IL-6 and TNF-α increase the total T-cell counts." (PMID 35903564, 2022). "Another study also showed that IL-6 levels are higher in patients with sepsis than in COVID-19 cases; however, IL-6 levels are still elevated in severe cases of COVID-19 compared to healthy patients." (PMID 36163447, 2022). "One study showed that levels of TNF-α, IL-6 and IL-8 were significantly lower in COVID-19 patients than in patients with bacterial sepsis with or without ARDS." (PMID 36289881, 2022). "This was detected in COVID-19 patients with high serum levels of IL-6 and low HLA-DR on their CD14 monocytes, along with a low lymphocyte count." (PMID 35062368, 2022). "Significant statistical variation was observed among COVID-19 disease severity groups in terms of IL-6 level (p < 0.001)." (PMID 35822078, 2022). "Regarding the composite endpoint 28-day mortality and/or intubation, Microcode performed similar to the known COVID-19 biomarker IL6 (AUC [95% CI] 0.90 [0.86–0.94, p < 0.0001] vs. IL6 0.88 [0.83–0.92, p < 0.0001])." (PMID 35723762, 2022).